ENSG00000264187 (novel protein)
Gene: Protein-coding gene on chromosome 17 (17,202,649 to 17,237,185, reverse strand). Ensembl gene ENSG00000264187.
Genetic constraint (gnomAD): Missense variants: 120 observed, 135.21 expected, observed/expected ratio (o/e) 0.89, 90% interval 0.76 to 1.03. Synonymous variants: 40 observed, 51.22 expected, observed/expected ratio (o/e) 0.78, 90% interval 0.61 to 1.02.